MIR519D (microRNA 519d)
Synonyms: hsa-mir-519d; MIRN519D; mir-519d
Gene: MicroRNA gene on chromosome 19 (53,713,347 to 53,713,434, forward strand). Ensembl gene ENSG00000207981.
Gene Ontology:
Biological process: miRNA-mediated post-transcriptional gene silencing